NIPAL1 (NIPA like domain containing 1)
Description:
Acts as a Mg(2+) transporter. Can also transport other divalent cations such as Fe(2+), Sr(2+), Ba(2+), Mn(2+), Cu(2+) and Co(2+) but to a much less extent than Mg(2+) (By similarity).
Synonyms: NIPA3; NPAL1; DKFZp686A06115; SLC57A3
Tractability: Antibody: UniProt predicts a signal peptide or a membrane-spanning region. PROTAC: ubiquitination databases record sites on it.
Gene: Protein-coding gene on chromosome 4 (47,914,142 to 48,040,173, forward strand). Ensembl gene ENSG00000163293.
Subcellular location: Golgi apparatus membrane
Subcellular location (Human Protein Atlas): Golgi apparatus
Pathways (Reactome):
Transport of small molecules: Miscellaneous transport and binding events
Gene Ontology:
Molecular function: magnesium ion transmembrane transporter activity
Biological process: magnesium ion transport; magnesium ion transmembrane transport
Cellular component: Golgi apparatus; Golgi membrane; membrane
Genetic constraint (gnomAD): Loss-of-function variants: 24 observed, 26.02 expected, observed/expected ratio (o/e) 0.92, 90% interval 0.67 to 1.3. The upper end of that interval is the gene's LOEUF score, 1.3, which puts it in group 5 of 6, group 1 being the genes least tolerant of losing a copy. Missense variants: 334 observed, 398.02 expected, observed/expected ratio (o/e) 0.84, 90% interval 0.77 to 0.92. Synonymous variants: 131 observed, 155.33 expected, observed/expected ratio (o/e) 0.84, 90% interval 0.73 to 0.98.
Homologues: Orthologues: chimpanzee NIPAL1 (100% identical), macaque NIPAL1 (99% identical), dog NIPAL1 (92% identical), pig NIPAL1 (90% identical), guinea pig NIPAL1 (89% identical), rat Nipal1 (89% identical), rabbit NIPAL1 (88% identical), mouse Nipal1 (87% identical), tropical clawed frog nipal1 (64% identical), Caenorhabditis elegans nipa-1 (45% identical), Drosophila melanogaster spict (41% identical). Paralogues in human: NIPA2 (57% identical), NIPAL4 (52% identical), NIPA1 (34% identical), NIPAL2 (23% identical), NIPAL3 (22% identical).
Diseases named in the same sentence as NIPAL1 in open-access papers:
NIPAL1 is named in the same sentence as 11 diseases in open-access papers, as found by Europe PMC text mining. Sharing a sentence is not in itself a finding about the gene and the disease. The quoted sentences say what the papers report.
gout (6 papers, 2018 to 2024). A condition characterized by painful swelling of the joints, which is caused by deposition of urate crystals. "A NIPA like domain containing 1 (NIPAL1) encodes a magnesium transporter, which is associated with recurrent oral squamous cell carcinoma, colon cancer, gout and neurodevelopment." (PMID 32906628, 2020). "The GWAS in Japanese male cohort showed that rs11733284 of NIPAL1 gene was associated with renal underexcretion gout." (PMID 30123371, 2018). "Interestingly, NIPAL1 is also associated with gout in a GWAS of more than 4000 Japanese men45." (PMID 38778091, 2024). "A recent GWA study of gout and its subtypes revealed that HIST1H2BF-HIST1H4E, NIPAL1, and FAM35A were novel risk loci." (PMID 30189835, 2018).
oral squamous cell carcinoma (2 papers, 2020 to 2021). "Immunostaining observed that its family member NIPAL1 was expressed in 20.3% of oral squamous cell carcinoma patients." (PMID 34211824, 2021). "siRNA-mediated knockdown of NIPAL1 significantly inhibited the growth and adhesion of oral squamous cell carcinoma cells compared with negative siRNA." (PMID 34211824, 2021).
E. coli infection (1 paper, 2020). "The results of this study indicated that miR-215 could regulate E. coli infection by targeting EREG, NIPAL1 and PTPRU genes." (PMID 32906628, 2020).
esophageal squamous cell carcinoma (1 paper, 2026). Esophageal squamous cell carcinoma (ESCC) is a type of esophageal carcinoma (EC) that can affect any part of the esophagus, but is usually located in the upper or middle third. "Here, we identify a NIPAL1-driven metabolic-epigenetic circuit in esophageal squamous cell carcinoma (ESCC) that facilitates tumor growth and suppresses antitumor immunity." (PMID 41816976, 2026).
tumor (5 papers, 2019 to 2026). "Our findings reveal a previously unrecognized NIPAL1-HCK-H3K18la signaling loop that integrates tumor metabolism to immune regulation, offering promising targets to improve immunotherapy efficacy in ESCC." (PMID 41816976, 2026). "We specifically confirmed the differential expressionof three Golgi-related genes (NIPAL1, PARP 10 and ZYG11B) between tumor andpara-cancer tissue." (PMID 41020586, 2025). "For example, NIPA1 and NIPAL1 were related with poor prognosis of cancers, and MAGT1 knockdown inhibited tumor progression." (PMID 39242581, 2024).
cancer (4 papers, 2021 to 2025). A tumor composed of atypical neoplastic, often pleomorphic cells that invade other tissues. "High NIPAL1 expression significantly correlated with cancer cell intravasation and poorer disease-free survival." (PMID 34211824, 2021). "Studies have shown that the expression of MAGT1 impacted the progression of cancer, and NIPA1 and NIPAL1 were related with poor prognosis." (PMID 39242581, 2024). "Furthermore, we analyzed our original chromatin accessibility data,and found that the DNA binding motifs of ELF1, JUND, and SPI1, which arepotential transcription factors of PARP10, NIPAL1 and ZYG11B in CRC tissues, arespecifically open in cancer tissues compared with adjacent tissues." (PMID 41020586, 2025).
NIPAL1 also shares sentences with these, for which no sentence is quoted: colon cancer (1 paper); COVID-19 (1); diabetes (1); esophageal cancer (1); primary immunodeficiency (1).